CEACAM6 (CEA cell adhesion molecule 6)
Diseases named in the same sentence as CEACAM6 in open-access papers (continued):
Sharing a sentence is not in itself a finding about the gene and the disease.
tumor (continued). "Thus, for CEACAM6, it was found that 8 of the 9 high PDEF expressing tumors also showed high CEACAM6 expression (tumors #1-9, except tumor #3)." (PMID 23592399, 2013). "Finally, we found that overexpression of CEACAM6 resulted in a modest increase in the expression of the proliferation marker, PCNA, when compared to control tumours." (PMID 23021083, 2012). "The present study suggests that the focal pattern of CEACAM6 expression, in tumours, is derived from a specific clonal progenitor within the tumour rather than being transiently induced by the local environment." (PMID 23021083, 2012). "Nevertheless, because of their ectopic or deregulated overexpression in up to 70% of all tumours, CEACAM5 and CEACAM6 represent popular targets for novel cancer therapies, including cancer vaccines, cellular immunotherapy, radioimmunotherapy, and antibody therapy." (PMID 17576469, 2007). "This, as well as the likelihood that many may have lacked appreciable tumor CEACAM6 expression, may provide direction for design of future L-DOS47 combination studies." (PMID 40860822, 2025). "Likewise, CEACAM6, also known as CD66c and nonspecific cross-reacting antigen NCA, is a tumor-associated antigen that plays a crucial role in cell adhesion." (PMID 41233805, 2025). "Similarly, the NEO-201 monoclonal antibody has been shown to bind to tumor-associated variants of CEACAM5 and CEACAM6 in cancerous but not normal tissue." (PMID 40860822, 2025). "Due to the lack of CEACAM6 in mice, the most appropriate experimental models may be the 3D co-culture in vitro models of tumor microenvironment and humanized mouse models." (PMID 38279989, 2024). "Since HL-60 and U937 do not express CEACAM-5 or CEACAM-6, it is very likely that NEO-201 binds to different types of cancers expressing core 1 and/or extended core 1 O-glycans attached not only to the tumor-associated variant of CEACAM5 and CEACAM6 but also to other protein carriers." (PMID 36991390, 2023). "In addition, IHC analysis of different human tumor tissues confirmed that NEO-201 binds specifically to tumor cells expressing a tumor-associated variant of CEACAM-5 and CEACAM-6, while it does not react against healthy tissue." (PMID 35804808, 2022). "Furthermore, both HL-60 and U937 do not express CEACAM5 and CEACAM6, suggesting that NEO-201 can bind to core 1 and extended core 1 O-glycans attached to any tumor-associated protein containing the amino acids serine and threonine." (PMID 36291783, 2022). "CEACAM6 (carcinoembryonic antigen-related cell adhesion molecule 6) belongs to the carcinoembryonic antigen (CEA) family of glycosylphosphatidylinositol- (GPI-) anchored cell surface glycoproteins and plays a role in tumor cell migration, invasion, adhesion, and formation of distant metastases." (PMID 30809317, 2019). "Consequently, the body’s immune response weakens and can no longer resist the tumor promoting effects induced by the overexpression of CEACAM6, leading to poor OS." (PMID 28883649, 2017). "This difference in CEACAM6 biliary levels between EHCC and IHCC may be attributable to inherent differences in protein expression and/or excretion, contact time between bile and tumor cells, and/or some degree of biliary obstruction." (PMID 26974538, 2016). "Since PDX models do not have an appropriate negative control of normal tissue with human CEACAM6, we correlated the fluorescent signal of the Alexa Fluor 488 anti-CEACAM6 conjugate with the amount of CEACAM6 estimated for each tumor by quantitative histopathology." (PMID 27421133, 2016). "So far, we have performed experimental validation on four of the identified candidates (GLIPR1L1, GHSR, CEACAM6, and CCR9, of which we here report on CCR9) using additional tumor cell lines and antigen-specific CTL clones and in all cases we could confirm their immune-modulatory function." (PMID 25691366, 2015).
tumor (continued). "Thus, we conclude that CEACAM6 induces EMT by activating the PI3K/AKT signaling pathway in GC and may serve as a potential target in tumor treatment." (PMID 25398131, 2014). "Moreover, we show that the knockdown of CEACAM6 results in a decrease, but not an ablation, of tumour initiating activity or tumour growth." (PMID 23021083, 2012). "In contrast, neither CEA nor CEACAM6 mRNA levels were decreased in tumour tissue." (PMID 16755296, 2006). "Moreover, we observed that immune‐related and cell adhesion‐related genes such as CD83, HLA‐DRA, JAK3, CEACAM6, and ITGB238, 39, 40, 41 exhibited high H3K27me3 modification in tumour cells, suggesting that their expression may be suppressed by H3K27me3 to facilitate immune escape of tumour cells." (PMID 39210544, 2024). "Therefore, testing CEACAM6-targeted therapies in regular mouse systems can only provide information on the efficacy of the given strategy, but should not be directly interpreted in terms of off-tumor, on-target toxicities." (PMID 38279989, 2024). "Also, the mRNA levels of CEACAM1 and CEACAM6 (known membrane markers of malignant epithelial cells in various adenocarcinoma, including colon cancer), as well as MKI67 (a proliferation marker), were significantly higher at tumor center and tumor invasive margin than adjacent normal in PanCK(+) AOIs." (PMID 37964075, 2023). "In previous studies, we showed that NEO-201 specifically recognizes a tumor-associated variant of CEACAM5 and CEACAM6, which is not expressed in normal tissues, and proved that NEO-201 binds to both mammalian-expressed recombinant human CEACAM5 and CEACAM6 but not to CEACAM1 or CEACAM8 by ELISA." (PMID 36291783, 2022). "Thus, all tumor histotypes expressed significantly more CEACAM6 than non-neoplastic ovary." (PMID 17201906, 2007). "A novel antibody-drug conjugate that targets tumors expressing CEACAM6, L-DOS47 was designed to combat tumor acidity, for which no approved therapies currently exist." (PMID 40860822, 2025). "The specificity of CSF CEACAM6 for LUAD‐LM patients suggested that this molecule was an oncogenic protein, but not a tumor responsive protein." (PMID 36082960, 2023). "Some tumor areas showed overlap between CEACAM5 and CEACAM6, but this was not always the case." (PMID 38502695, 2024). "However, in HCC, CEACAM6 expression was not prominent, while CD24 expression was significantly higher compared to normal liver tissues, spatial transcriptomics (HRA000437) of patient tumor specimens corroborated the findings." (PMID 40860182, 2025).
cancer (121 papers, 2004 to 2026). A tumor composed of atypical neoplastic, often pleomorphic cells that invade other tissues. "A glycosylphosphatidylinositol-anchored cell adhesion molecule, CEACAM6 overexpression is associated with altered adhesion and invasion in many cancers, including NSCLC and pancreatic adenocarcinoma." (PMID 40860822, 2025). "Conversely, the mesenteric lesion had enriched expression of the keratin family genes (KRT7, KRT17) involved in cancer progression as well as metastasis signature associated gene CEACAM6." (PMID 40018643, 2025). "This supported the use of this anti-CEACAM6 antibody as a targeting component in L-DOS47 development for treatment of CEACAM6-expressing cancers with reduced risk of off-target effects." (PMID 40860822, 2025). "The expression of CEACAM6 has been associated with the prevention of apoptosis, the promotion of drug resistance, and enhanced cancer cell invasion and metastasis." (PMID 39767561, 2024). "CEACAM6 belongs to the immunoglobulin superfamily and is implicated in various cellular processes that facilitate cancer progression." (PMID 39767561, 2024). "Expression of CEACAM6 associates with cancer cell proliferation, migration, invasion, and angiogenesis in several types of cancers including cholangiocarcinomas (CCAs)." (PMID 34359854, 2021). "The antigen recognized by NEO-201, a variant of CEACAM-5 and CEACAM-6, is specific to cancer tissue but expressed across cancer subtypes." (PMID 32637350, 2020). "Conversely, the MDA-MB-468 cancer cell lines that were CEACAM6 antibody susceptible cancer cell line reduced in cell viability over time." (PMID 32357523, 2020). "Carcinoembryonic antigen-related cell adhesion molecule 6 (CEACAM6) is a member of the glycosylphosphatidylinositol-linked immunoglobulin superfamily that is implicated in many human cancers." (PMID 28883649, 2017). "Importantly, high expression of CEACAM6 is also associated with immune suppression and low cytolytic T-cell activity in cancers." (PMID 38279989, 2024). "Interestingly, APOBEC3B (A3B) a DNA cytosine deaminase, is a source of genomic DNA mutations that contributes to cancer progression and metastasis is significantly down-regulated in CEACAM6 KO cells." (PMID 31797958, 2019). "Carcinoembryonic antigen-related cell adhesion molecule 6 (CEACAM6) is a glycosylphosphatidylinositol (GPI)-linked immunoglobulin superfamily member that is overexpressed in a variety of human cancers, especially gastrointestinal cancers, and functions as an intercellular adhesion molecule." (PMID 25398131, 2014). "Suppression of the CEACAM6 transcripts using siRNA of CEACAM6 leading to a reduction in cancer cell invasiveness, may be associated with an increase in E-cadherin promoter activity." (PMID 23251258, 2013). "Particularly, cumulative evidence from preclinical and clinical data together revealed a more complex influence, in particular for CEACAM1, CEACAM5, and CEACAM6 on cancer and CSCs." (PMID 41233805, 2025). "Several studies have highlighted carcinoembryonic antigen cell adhesion molecule 6 (CEACAM6) as a potential therapeutic target for various cancers." (PMID 40282889, 2025). "The miR-29 family (miR-29a/b/c) regulates multiple signaling pathways involved in cancer progression and has been shown to inhibit CEACAM6 transcription." (PMID 40282889, 2025). "Carcinoembryonic antigen-related cell adhesion molecule 6 (CEACAM6) is emerging as a crucial determinant of the malignant phenotype in a range of cancers, including PC." (PMID 40619414, 2025). "Recent findings suggest that CEACAM6 lactylation improves its stability, modulates cancer cell sensitivity to 5-fluorouracil, and induces chemotherapeutic resistance in CRC cell lines (HT29 and WiDr)." (PMID 40994548, 2025). "Recent studies have investigated CEACAM6 for its role in cancer development and progression and have shown its potential as a therapeutic target for several malignancies." (PMID 40282889, 2025).
cancer (continued). "Through correlation analysis, we observed that LAD1 expression levels were statistically associated with several cancer-related genes, including SFTPB, S100A6, CEACAM6, KRT19, S100A10, ANXA2, S100A11, and CAPN2." (PMID 41423496, 2025). "CEACAM6 is highly expressed in malignant tumors and results in resistance to multiple chemotherapeutic agents." (PMID 40994548, 2025). "Members of this family, including human CEACAM1, CEA, and CEACAM6, are found on various epithelial cell types and derived carcinomas." (PMID 41373727, 2025). "This review aims to provide a comprehensive summary of CEACAM6’s role in different cancer types, its involvement in signaling pathways, and recent advancements in CEACAM6-targeted treatments." (PMID 38796667, 2024). "This line of investigation has been supported by in vitro observations that genetic downregulation of CEACAM6 results in decreased cellular invasiveness, reduction in the anoikis resistance and suppression of metastatic potential in cancer cells." (PMID 38279989, 2024). "Since L-DOS47 is suitable for cancers that express high levels of its target antigen CEACAM6, pancreatic and gastrointestinal cancers are other potential applications in addition to lung cancer." (PMID 38398062, 2024). "Because of its recognized role in cancer development and progression, CEACAM6 has become an attractive therapeutic or theragnostic target in a number of malignancies." (PMID 38279989, 2024). "When CEACAM6 was used to distinguish benign from malignant tumors, it showed higher sensitivity (100%) compared to other biomarkers." (PMID 38796667, 2024). "The knockdown of CEACAM6 did not only inhibit cancer cell migration by increasing cell adhesiveness but also reduced overall cell vitality, increased senescence, and led to a block in cell cycle progression." (PMID 39468006, 2024). "Deregulated expression of CEACAM6 directly affects the biology of cancer cells, e.g., by decreasing differentiation, inhibiting anoikis or indirect increase in the metastatic potential." (PMID 38279989, 2024). "Other consequences of aberrant CEACAM6 expression in cancer cells include increased proliferation and chemoresistance." (PMID 38279989, 2024). "Although we also found enrichment of CEACAM5, we focused further studies on CEACAM6 as it was more strongly correlated with acid resistance and had been less extensively explored as a target for cancer therapy." (PMID 38502695, 2024). "Acid-resistant cell lines were characterized by high levels of CEACAM6, a protein found at the surface of cancer cells and also present in late-stage disease in human cancers." (PMID 38502695, 2024). "As an important pathological biomarker in cancer, targeting CEACAM6 or the signaling pathway mediated by CEACAM6 has garnered significant attention in recent years." (PMID 38796667, 2024). "Our functional analyses in vitro and in vivo mouse models revealed that CEACAM6 supported the initial steps of cancer progression and metastasis by decreasing cell adhesion and promoting migration and invasion of GBC cells." (PMID 39468006, 2024). "The review elucidates the diverse mechanisms regulating CEACAM6 expression and its consequent impact on cancer progression, encompassing both its promotive and suppressive roles in various cancer types." (PMID 38796667, 2024). "This is due to the higher expression of CEACAM6 in cancer, as well as its correlation with prognostic indicators such as disease-free survival (DFS) and overall survival (OS)." (PMID 38796667, 2024). "The evidence supporting the role of CEACAM6 in cancer biology underscores its potential as both a therapeutic target and a biomarker for various malignancies." (PMID 39767561, 2024). "Numerous studies have demonstrated that CEACAM6 expression is markedly elevated in multiple types of cancer, including breast, colorectal, gastric, non-small cell lung, and pancreatic cancers." (PMID 39767561, 2024).
cancer (continued). "This review aims to provide a thorough understanding of CEACAM6’s role in cancer, serving as a foundation for future research and development in cancer therapeutics." (PMID 38796667, 2024). "Among the upregulated genes we noticed markers those were associated with cancer genesis and development, including SOX4, SPINK1, CEACAM6, KRT8 and KRT18." (PMID 37957625, 2023). "A major malignancy-specific feature identified was carcinoembryonic antigen 6 (CEACAM6), known oncogenic gene overexpressed in numerous cancers including non-small cell lung (NSCLC), colon, and breast cancers." (PMID 36906603, 2023). "Depending on the cell type, CEACAM1, CEACAM5, and CEACAM6 play pivotal roles in particular aspects of cancer biology and immunology." (PMID 36741860, 2023). "The carcinoembryonic antigen‐related adhesion molecules (CEACAMs) are a large family, among which CEACAM5 (CEA) and CEACAM6 are recognized as related to cancer processes." (PMID 36082960, 2023). "Elevated serum levels of soluble MICA and soluble CEACAM-5 and CEACAM-6 have been correlated with impairment of NK cell activity, cancer progression and metastasis." (PMID 36991390, 2023). "The results revealed that the cancer cell subclusters c8_TOP2A, c9_HMGB2, c12_MKI67, and c13_TK1 were dominantly in a cycling state, while c1_TCN1, c2_CD74, c3_CD24, c5_CEACAM6, and c10_SAT1 were mainly in a quiescent state." (PMID 36529697, 2023). "CEACAM6, overexpressed in several cancers and in gastrointestinal tumors or in mucin-producing carcinoma, is implicated in metastatic activity by promoting EMT." (PMID 35328744, 2022). "In the current review article, we discuss and evaluate potential nanomaterial targeting of integrin αvβ3, carcinoembryonic antigen cell adhesion molecule 6 (CEACAM6), and novel nanomaterial delivery therapeutic strategies for cancers." (PMID 34359854, 2021). "We demonstrated that CEACAM6 expression was significantly upregulated in cancer tissues that had high TNFRSF11B expression." (PMID 34938284, 2021). "Carcinoembryonic antigen cell adhesion molecule 6 (CEACAM6) activates the downstream integrin FAK to stimulate biological activities including cancer proliferation and metastasis." (PMID 34359854, 2021). "Our study showed that inhibition of cancer proliferation and tumor growth by anti-CEACAM6 antibodies inhibits levels of Tyr397 FAK phosphorylation to suppress FAK-activated signaling pathways." (PMID 34359854, 2021). "CEACAM6 was reported to be overexpressed not only in the cancer tissue and blood serum of PDAC patients, but also in their bile." (PMID 34207784, 2021). "According to the data provided above, CEACAM6 mRNAs were over expressed in both the Dys and Cancer groups." (PMID 34221964, 2021). "Expression of CEACAM6 in pancreatic, gastric, and other cancers was previously shown to predict poor survival and advanced metastatic progression." (PMID 34625644, 2021). "Hybridoma cells were encapsulated within the PSF MTAMs, where they produced CEACAM6 antibodies to be used in the suppression of cancer cell line A549, MDA-MB-468 and PC 3 (control)." (PMID 32357523, 2020). "At present, our team also study the targeted inhibitory effect of PE38KDEL toxin regulated by the specific expression of the CEACAM6 gene in cancer." (PMID 32017381, 2020). "CEACAM6 is overexpressed in a wide variety of cancers and can even be used as a marker for isolating cancer stem cells in colorectal cancer." (PMID 32648688, 2020). "Conversely, both A549 and MDA-MB-468 cancer cell lines were susceptible to the effects of CEACAM6 antibodies, with MDA-MB-468 possessing more binding site as compared to those found in A549 cancer cell line." (PMID 32357523, 2020). "In this study, we only utilized three different cells, namely, hybridoma as the source of the CEACAM6 antibody, PC 3 as a non CEACAM6 susceptible cancer cell line and MDA-MB-468 as a CEACAM6 antibody susceptible cancer cell line." (PMID 32357523, 2020).